BCL6 (BCL6 transcription repressor)
Diseases named in the same sentence as BCL6 in open-access papers (continued):
Sharing a sentence is not in itself a finding about the gene and the disease.
tumor (continued). "Thus, SCC7 tumor-bearing C3H mice were randomly divided into four treatment groups: i) control; ii) anti-PDL1 antibody; iii) Bcl6 inhibitor FX1, and iv) combination therapy of FX1 and anti-PDL1." (PMID 40290124, 2025). "As an oncogene, BCL6 exerts its transcriptional repression activity by recruiting transcriptional corepressors through its BTB domain, thereby suppressing its target genes, promoting cancer cell proliferation and tumor progression." (PMID 39815148, 2025). "Additionally, the tumor is strongly positive for both MYC and BCL6, classifying it as double-hit lymphoma, or the double-expressor type, which is associated with an extremely poor prognosis and a median survival of 12-18 months." (PMID 39651017, 2024). "IHC studies revealed that the tumor cells expressed CD20, BCL2, and BCL6." (PMID 36342081, 2023). "The tumor was cytotoxic (perforin+) with coexpression of PD1 and BCL6." (PMID 37500795, 2023). "In some cases, such as the highly mutated BCL2 and BCL6, individual TFA-BT NCVs are generally not recurrent but affect the binding of the same TFs at different positions in the promoter across tumor samples." (PMID 36808133, 2023). "Furthermore, tumor-derived redHMGB1 was identified as the priming signal, which, through TLR4 and mTOR/AKT pathway, induced Bcl6-driven program underpinning SMMs generation." (PMID 36542153, 2022). "Since we identified BCL6 as what we believe to be an effector downstream of ERK, BCL6i may provide a potential means to block tumor cells with access to ERK reactivation." (PMID 36377663, 2022). "Given that the MAPK/ERK/ELK1 axis regulates BCL6 expression, we additionally explored whether BCL6 pharmacological inhibitors, such as COMP7, in combination with MEKi, could lead to more potent tumor inhibition than single-agent treatment." (PMID 36377663, 2022). "We next sough to address whether resumption of Bcl6 would restore SMM generation in TLR4−/− macrophages, the population proved to be unable to induce Bcl6 upon tumor stimulation." (PMID 36542153, 2022). "Accordingly, deletion of Tet2 failed to fully activate SMM-related genes in tumor-conditioned macrophages even with Bcl6 overexpression." (PMID 36542153, 2022). "The effect however could not be reproduced in TLR4 null macrophages, corroborating that tumor-derived redHMGB1, via TLR4-sensing pathway, initiated the mTOR/Bcl6 program in macrophages." (PMID 36542153, 2022). "We further used the myr-AKT plasmids to show that constitutive activation of AKT largely restored mTOR activation and subsequent Bcl6 expression even with no tumor instruction." (PMID 36542153, 2022). "Our findings strengthened the connection between BCL6 and PTEN that might commonly occur in germinal center B cells and tumor cells." (PMID 35503721, 2022). "Additionally, our data reveal that tumor-derived redHMGB1 serves as the priming signal to be sensed by TLR4 and initiate the mTOR/Bcl6-driven program for SMMs development." (PMID 36542153, 2022). "BCL6 knockdown or paclitaxel treatment modestly reduced MDA‐MB‐231 tumor growth; however, the combination of BCL6 knockdown and paclitaxel resulted in significant reduction in tumor volumes and weights." (PMID 33932086, 2021).
tumor (continued). "Despite that Bcl6 antagonizes Blimp1 in many cell types, Bcl6 was not altered in TIL Blimp1-deficient Treg cells, suggesting a Bcl6-independent role of Blimp1 in the regulation of tumor immunity." (PMID 34798898, 2021). "A recent study found that Bcl6 was essential in maintaining the lineage stability of Treg cells in TME and deletion of Bcl6 in Treg cells resulted in impaired suppressive function and tumor regression." (PMID 33748292, 2021). "i.e., miR-155, miR-17-92 and miR-21 act as oncogenes by altering the expression levels of MYC, SHIP and FOXO1, respectively, conversely; miR-34a, mir-144 and miR-181a act as tumor suppressors by altering the expression levels of SIRT1, BCL6 and CARD11, respectively." (PMID 34679437, 2021). "However, the clear trend observed in this overall survival study suggests a promising tumour suppressor function for BACH2 and BCL6." (PMID 35008187, 2021). "The remainder of the cases are of a germinal center B-cell (GCB) subtype, which is defined by CD10 expression in at least 30% of tumor cells or Bcl-6 expression in the absence of MUM1 expression." (PMID 33322508, 2020). "ZBTB16 functions as a tumor suppressor through upregulating ZBTB28 and antagonizing BCL6." (PMID 32517789, 2020). "Furthermore, ectopically expressed ZBTB16 formed heterodimers with ZBTB28 or BCL6/ZBTB27 and exerted tumor suppressor effects through upregulation of ZBTB28 and antagonistic activity on BCL6." (PMID 32517789, 2020). "These tumor cells sharetrisomy 12 as a common genetic abnormality, and it is speculated that trisomy 12 may have occurred earlier than BCL2 and BCL6 translocations." (PMID 35847735, 2020). "Tumor-infiltrating CD62L+ Bcl6+ T cells did not express PD-1, and had a high potential to expand and differentiate into effector T cells." (PMID 32845913, 2020). "Initial tumor stasis was followed by slow tumor growth, which can be attributed to the selection of cells lacking a functional BCL6 knock-out." (PMID 32180900, 2020). "However, the addition of a fourth oncogene (BCL6, BCL2, P53dd, and CCND3) led to tumor formation with a median of 112 days." (PMID 31586074, 2019). "This BCL6 inhibitor inhibits tumor growth in mice xenografted with DLBCL cells without any toxicity." (PMID 31336593, 2019). "The coexpression of BCL6 and IL21 in some of these PD-1+ cells indicates that Tfh differentiation occurs in the tumor microenvironment, presumably through the repeated and chronic exposure to quasi-self antigens (i.e., tumor antigens)." (PMID 30061879, 2018). "However, similar to BCL6 and BCL2, KDSR is differentially expressed between tumor and normal paired FL samples (KS-test P < 0.001)." (PMID 28765546, 2017). "Patients with tumor tissue Bcl-2 positive and Bcl-6 negative (Bcl-2+/Bcl-6-) have the worst outcomes." (PMID 27129176, 2016). "No clinicopathologic features were significantly different between DLBCL patients with concurrent MYC/BCL6 rearrangements versus patients without MYC/BCL6 concurrent rearrangement, although larger tumor size was of borderline significance (P = 0.058)." (PMID 26573234, 2016). "After measuring the expression levels of miR-10a and BCL6 in human DLBCL tumor tissues and paired non-neoplastic lymphatic tissues, we confirmed an inverse correlation between miR-10a and the BCL6 protein levels." (PMID 27815824, 2016). "Briefly, germinal center-like (GC) type CNS DLBCL fulfilled the criteria of either expressing CD10 in>30% of the tumour cells or being BCL6 positive and CD10/MUM1 negative." (PMID 25268364, 2014). "Immunohistochemically, the tumor cells were strong positive for CD56, CD3ε, TIA1, and weak positive for LMP1, and negative for CD5, CD8, CD20, CD79a, CgA, Syn, SCLC, CK, EMA, CD99, CD10, TdT, PAX-5, and BCL-6." (PMID 23958352, 2013). "The large tumor cells express B-cell markers CD20 and bcl-6." (PMID 20218944, 2010).
tumor (continued). "In the present study, the antitumor efficacy of Fx1 relied on immune cells, suggesting BCL6 expression in MC38 or B16F10 tumor cells likely did not reflect a direct antitumor effect, though inhibiting BCL6 in tumors may benefit tumor growth resistance as well." (PMID 41145211, 2026). "Moreover, tumor-infiltrating CD8 T-cell levels and Bcl6 expression showed a positive correlation in COAD, PAAD, and READ samples, suggesting that tumor-intrinsic BCL6 expression is associated with a more aggressive malignant phenotype, even in the presence of increased T-cell infiltration." (PMID 41145211, 2026). "In this study, we found that inhibition of BCL6 in activated CD8 T cells increased the expression of glucose transporter GLUT3, thereby maintaining glycolysis, and indicating that retarding T-cell exhaustion in tumor conditions is a plausible therapeutic strategy." (PMID 41145211, 2026). "To confirm whether the BCL6-PLAAT4 axis plays the same role in vivo as that in vitro, we established a subcutaneous transplantation tumor and abdominal metastasis model of the SKOV3 cells in nude mice following replenishment of either BCL6 gene or co-replenishment of both BCL6 and PLAAT4." (PMID 40777995, 2025). "Interestingly, unlike the phenotype observed in immune competent mice, tumor growth was no longer affected by Bcl6 knockout or overexpression in nude mice." (PMID 38956432, 2024). "Next, to study Bcl6 function in vivo, H22 cells line was labeled with luciferase using protocol 18, thus we could use in vivo imaging system (IVIS) to monitor the tumor growth in a real-time manner." (PMID 38956432, 2024). "Tumor cells are typically positive for Bcl-6 and negative for CD10." (PMID 37000052, 2023). "Therefore, BCL6 could directly repressed the transcription of FZD7 to inhibit the Wnt/β-catenin signaling pathway and acted as a tumor suppressor in GC." (PMID 37060074, 2023). "The tumor cells were negative for CD10 but positive for BCL6 and MUM-1." (PMID 37884941, 2023). "In addition, the tumor cells were positive for BCL-6 (G/191E/A8) andCD10 (SP67, Ventana) and negative for Cyclin D1 (SP4-R, Ventana) and MUM-1 (MUM1p, Dako)." (PMID 37202787, 2023). "Interestingly, we observed that Bcl6+ macrophages persisted for at least 6 weeks in the in vitro culture with no tumor signaling input." (PMID 36542153, 2022). "Our present study demonstrates that Bcl6+ TAMs and their sibling cells stably maintain stem-related gene signature, self-renewing property and pro-tumor memory, even after culturing for an extended period in the absence of tumor stimulation." (PMID 36542153, 2022). "However, the role of Bcl6 in Treg cells function has not been completely elucidated, particularly in terms of anti-tumor immune response." (PMID 32477338, 2020). "However, we examined this carefully and are confident that BCL6 expression reported here is in the tumor cells, and not any immune compartment." (PMID 32320427, 2020). "Also in our model the editing efficiency of CRISPR on BCL6 is not 100% as a low percentage of tumor cells maintain BCL6 expression after DOX treatment." (PMID 32180900, 2020). "Lack of Bcl6 in tumor-infiltrating CD62L+ T cells impaired the ability to expand." (PMID 32845913, 2020). "SU-DHL-4 control cells and BCL6 sgRNA cells showed a comparable tumor growth (data not shown)." (PMID 32180900, 2020). "Additionally, this compound could induce expression of BCL6 target genes, kill BCL6-positive DLBCL cells and potently suppress tumor growth in human DLBCL xenografts models." (PMID 31788471, 2019). "In this pathological setting, it is conceivable that Bcl-6 blockade by 79-6 could not further enhance tumor-driven angiogenesis." (PMID 27880939, 2017). "Given that rearrangements in the Bcl-6 gene are seen in approximately 30% of diffuse large B cell lymphomas, some authors have speculated that the close relationship of p63 to Bcl-6 may contribute to its potential involvement in DLBCL tumor progression." (PMID 27648316, 2016).
tumor (continued). "Inhibition of BCL6 with the small molecule inhibitor 79-6 resulted in a significant decrease in expansion of ALL cells in media alone compared to DMSO solvent controls without an effect on tumor cell viability." (PMID 27015556, 2016). "The lack of BCL-6 expression and M protein secretion indicated that the tumor cell may have originated from post-germinal center plasma cells." (PMID 25364423, 2014). "Interestingly, tumor cell emboli were observed in MCF-7-BCL6 xenografts but not in the control xenografts, suggesting that BCL6 expression potentially promoted tumor cell invasion and metastasis." (PMID 24917186, 2014). "We first depleted BCL6 expression by siRNA and co-transfected the cells with miR-339-5p ASO and observed that depletion of BCL6 expression significantly abrogated miR-339-5p ASO-induced tumor cell migration and invasion, indicating that BCL6 plays a critical role at the downstream of miR-339-5p." (PMID 24917186, 2014). "Thus, the targeting of BCL6 and STAT6 in addition or prior to the treatment with components of the current immuno-chemotherapy may sensitize the PMBL tumor cells for drug effects, at least in parts of PMBL cases." (PMID 25594020, 2014). "Additionally, the immunohistochemical evaluation revealed that the null expression of CD10 and Bcl-6 excludes the follicular origin of this tumour." (PMID 23420489, 2013). "This population included a strong proportion of tumor antigen-specific T cells and of BCL6+CD122+ T cells that might share functional properties with stem-like CD8+ T cells and could explain why the Vox+anti-PD-1 antibody combination offers protection against tumor rechallenge." (PMID 40139833, 2025). "In summary, we identified WK369 as a novel BCL6 small molecular inhibitor, which could significantly inhibit the growth and migration of OV in vitro and in vivo without toxicity and prolonged the survival of tumor-bearing mice." (PMID 38169532, 2024). "However, after Bcl6 knockout, depletion of CD4+T cells could rescue the tumor growth to the level which is comparable to combined depletion of CD4+T cells and CD8+T cells group, while depletion of CD8+T cells could only slightly increase tumor growth." (PMID 38956432, 2024). "However, immunohistochemistry of the tumor showed negative staining for BCL-6." (PMID 33811277, 2021). "However, the role of Bcl6 in the progression of NASH or NASH-derived tumours has not been studied." (PMID 32546802, 2020). "IHC confirmed the diagnosis of DLBCL (germinal center B-cell subtype), as the tumor cells were positive for Oct-2, CD20, PAX5, BCL-6, and CD10 and negative for CD38, CD138, MUM1, and CD30." (PMID 40432631, 2025). "Immunohistochemistry confirmed DLBCL (germinal center B-cell subtype), with tumor cells positive for Oct-2, CD20, PAX5, BCL-6, and CD10 and negative for CD38, CD138, and MUM1." (PMID 40432631, 2025). "Morphologically, the tumor comprised a subset of lymphoid cells with centrocytic morphology that was positive for CD20, PAX5, CD10, BCL6, and CD23, and negative for CD5 and BCL2." (PMID 40861583, 2025). "Both B and Tfh cells were critical for tumor control, as implanting tumors in mice lacking B cells (uMT mice), functional MHC-II (CDIIA knockout mice), and Tfh cells (Bcl6 knockout in the CD4 lineage) resulted in increased tumor growth." (PMID 40356924, 2025). "In the present study, SCC7 cells exhibited a similar level of Bcl6 compared with normal mouse oral epithelial cells (data not shown), which excluded the effect of FX1 on the tumor cell." (PMID 40290124, 2025).
tumor (continued). "These cells tested positive for CD10, CD79a, PAX-5, BCL-2, BCL-6 (10-20%), and c-MYC, but most tumor cells were negative for CD20 on immunohistochemistry." (PMID 41142614, 2025). "Immunohistochemically, the tumor cells were positive for ki-67, bcl-2, CD10, bcl-6, and CD38, but negative for bcl-2 and MUM-1." (PMID 39993110, 2025). "Immunohistochemical results showed that the tumor cells were positive for CD20, Bcl6, and MUM-1 but negative for CK (AE1/AE3), ER, PR, CD3, and CD10." (PMID 37884941, 2023). "By immunohistochemistry (IHC), the tumor cells were positive for CD20 and BCL‐6 and negative for CD10." (PMID 37206267, 2023). "The tumor cells were negative for MYC and BCL2 rearrangements but positive for BCL6 rearrangement by fluorescent in situ hybridization." (PMID 37884941, 2023). "In situ and ex vivo analysis featured such tumours as activated type of diffuse large B cell lymphoma (ABC-DLBCL), expressing BCL2 and c-MYC, but not BCL6, with activated STAT3 signaling." (PMID 36503430, 2022). "CTC CNAs, including amplifications of MYC, BCL6, DDR2, SOX2 and deletions of CDKN2A/B, were more likely to be shared with residual rather than primary tumor." (PMID 35087134, 2022). "The scarcity of tumor cells in tumor biopsies did not enable the performance of molecular analysis, especially to investigate MYC, BCL2, or BCL6 rearrangement." (PMID 35538643, 2022). "The tumor cells are positive for CD45, CD30, CD15, MUMi, and Ki-67 (80%) and negative for CD20, PAX-5, CD79a, CD3, CD5, CD10, BCL6, BCL2, EMA, ALK-1, and CD138." (PMID 34900354, 2021). "Immunohistochemical analysis of the left pleural biopsy specimens suggested DLBCL, where the tumor cells were positive for CD20, PAX5, and BCL-2 but negative for CD10, BCL-6, Mum-1, and LMP-1." (PMID 33564306, 2021). "In the undiluted tumor samples not more than 75 K on-target reads were needed to robustly detect the MYC, BCL2, and BCL6 rearrangements." (PMID 34099699, 2021). "Likewise, to explore whether miR-144-3p is relevant to endogenous BCL6 expression in human CRC, immunohistochemical staining and qRT-PCR assay were performed to determine the mRNA and protein level of BCL6 in 20 pairs of CRC tissues and non-tumor adjacent tissues." (PMID 32206063, 2020). "Immunohistochemical analysis showed that the tumor cells were positive for CD20, BCL2, BCL6, and MUM-1 and were negative for CD5 and CD10." (PMID 33071959, 2020). "However, it remains not fully investigated whether BCL6 is relevant for tumor maintenance." (PMID 32180900, 2020). "IHC was mainly positive for tumor markers like CD10, CD20, CD45, CD 79a, PAX5, MUM1, and BCL6, and negative for BCL2, ALK, CD30, and cyclin D1." (PMID 30764662, 2018). "We further identified an inverse correlation between miR-10a levels and BCL6 protein levels, but not mRNA levels, in DLBCL tumor tissue samples." (PMID 27815824, 2016). "Immunohistochemical staining was also performed and revealed the tumor to be CD10+, CD3+, CD79+ and negative for BCL6 and MUM1." (PMID 25294404, 2014). "Immunohistochemical staining demonstrated that most tumor cells were positive for B- cell markers such as CD20, bcl-6, and multiple myeloma oncogene 1 (MUM1), whereas those same tumor cells were negative for CD3, CD5, CD10, or bcl-2 (data not shown)." (PMID 22927863, 2012). "The recurrent tumor showed negativity for CD10, IgG, IgG4, IgM, cyclin D1, Bcl-6, CK (AE1/3), and Helicobacter pylori (data not shown) except that the recurrent tumor showed negativity for lambda and weak positivity for kappa." (PMID 21892966, 2011). "The primary tumor cells were positive for bcl-2, CD20, CD43, CD79a, Lambda, Kappa and was negative for CD10, IgG, IgG4, IgM, cyclin D1, bcl-6, CK (AE1/3), and Helicobacter pylori (data not shown)." (PMID 21892966, 2011).